PIEZO1 (piezo type mechanosensitive ion channel component 1 (Er blood group))
Diseases named in the same sentence as PIEZO1 in open-access papers (continued):
Sharing a sentence is not in itself a finding about the gene and the disease.
glioblastoma (continued). "This suggests that the expression of Piezo1 regulates EMT, and maintains mesenchymal characteristics of glioblastoma cells." (PMID 40061015, 2025). "The combination of Piezo1 inhibitors and TKI drugs provides a new direction for future targeted therapy of glioblastoma." (PMID 40061015, 2025). "To understand the transcriptomic consequences of PIEZO1 depletion, we next performed bulk RNA sequencing of a patient-derived glioblastoma cell culture models with and without PIEZO1 knockout via CRISPR-cas9 gene editing." (PMID 40791371, 2025). "Research has indicated that PIEZO1 is not expressed in normal brain tissue but demonstrates high expression levels in glioblastoma." (PMID 40535121, 2025). "In line with this notion, several down-regulated genes are reported markers of glioblastoma CSCs including FABP7, TF and SLC2A3 (aka GLUT3), suggesting that knockdown of PIEZO1 may influence the maintenance of the cancer stem cell state 55,56." (PMID 40791371, 2025). "Downregulation of the expression of Piezo1 had a significant effect on the β1-integrin/FAK pathway, and also significantly affected the nuclear localization and activity of YAP, suggesting that Piezo1 promotes the progression of glioblastoma invasion through the β1-integrin/FAK/YAP axis." (PMID 40061015, 2025). "At the cancer stem cell level, Piezo1 is highly expressed in glioblastoma CSCs (GBM-CSCs) compared to non-CSCs, correlating with increased FA and contractile force." (PMID 40821847, 2025).
atherosclerosis (24 papers, 2020 to 2025). A disease characterized by the build-up of fatty material and calcium deposition in the arterial wall resulting in partial or complete occlusion of the arterial lumen. "Piezo1 serves as both a pathogenic promoting factor and a potential therapeutic target in the development of atherosclerosis." (PMID 41195420, 2025). "Our work also utilizes genetic tools to evaluate the role of Piezo1 mutations in oxLDL uptake and atherosclerosis." (PMID 39544498, 2024). "The opening of Piezo1 under high hydrostatic pressure has been found to disrupt pulmonary endothelial barrier function, remodel arteries during hypertension, and cause atherosclerosis during turbulence." (PMID 38690080, 2024). "Accordingly, the upregulation of Piezo1 has been linked to both atherosclerosis and inflammation, whereby disturbed blood flow leads to Piezo1- and Gq/G11-mediated integrin activation, resulting in NF-κB activation and atherogenesis." (PMID 38541702, 2024). "Recent studies have revealed that Piezo type mechanosensitive ion channel 1 (Piezo1) in macrophage has been implicated in atherosclerosis." (PMID 37588590, 2023). "Perhaps the pro-inflammatory effect of PIEZO1 under DF in the atherosclerosis animal model is caused by the dysfunction of those transcription factors." (PMID 35883633, 2022). "Beside earlier reports including that of alberran Juarez and others, Zhang and colleagues also recently reported a unique Piezo1 mediated molecular process of inflammation and atherosclerosis via annexin A2 associated integrin triggering." (PMID 35173527, 2022). "Disturbed flow leads to Piezo1-mediated inflammation, and Piezo1 deficiency in endothelium reduces atherosclerosis." (PMID 34445487, 2021). "We found that GsMTx4 not only resists chronic atherosclerosis but also exhibits anti‐inflammatory and antiatherosclerotic effects in DF‐induced atherosclerosis, indicating that the atheroprotective role of Piezo1 may be associated with disturbed flow." (PMID 39450718, 2024). "It was also found that when endothelial-specific Piezo1 or Gq/G11-deficient mice were induced, activation of integrins, activation of inflammatory signaling pathways was found to be reduced, and the area of atherosclerosis and the extent of atherosclerosis were both reduced to some extent." (PMID 36247424, 2022). "While beneficial effects of a PIEZO1 agonist in atherosclerosis have been suggested, there are many more suggestions of potential benefits of PIEZO1 inhibitors in this condition." (PMID 40849789, 2025). "More preclinical and clinical trials are needed in the future to validate the safety and efficacy of Piezo1 inhibitors or modulators, with the aim of providing new approaches and strategies for precision treatment of atherosclerosis." (PMID 41195420, 2025). "Overall, Piezo1 plays a core role in atherosclerosis, bridging the gap between mechanosensation and pathological signaling cascades." (PMID 41195420, 2025). "While Piezo1 deletion ameliorates atherosclerosis, it also exerts physiological anti-inflammatory effects via KLF4." (PMID 41372156, 2025). "Piezo1 is expected to become a potential therapeutic target for atherosclerosis and cardiovascular diseases." (PMID 39450718, 2024). "Our findings indicate that endothelial KDM5B expression induced by d‐flow via the Piezo1 pathway promotes atherosclerotic plaque formation, providing targets for the prevention or therapeutic intervention of atherosclerosis." (PMID 39643939, 2024).
atherosclerosis (continued). "Our observations revealed elevated Piezo1 expression in plaque tissue and ECs of apoE−/− atherosclerotic mice with chronic atherosclerosis and DF‐induced atherosclerosis." (PMID 39450718, 2024). "Immunohistochemistry of mouse and human atherosclerosis demonstrated higher levels of PIEZO1 protein in plaques, together with higher expression of CD68 positive monocytes and macrophage-like cells when compared with control artery." (PMID 39107572, 2024). "Time course transcriptome array of mouse aortic lesion confirmed that Piezo1 expression increased with atherosclerosis progression." (PMID 39107572, 2024). "There is paucity of information on the role of PIEZO1 in macrophages and foam cells, especially in the context of atherosclerosis." (PMID 39107572, 2024). "Here, we present the first evidence that the calcium channel PIEZO1 regulates macrophage functions critical for progression of atherosclerosis." (PMID 39107572, 2024). "Next, we induced a DF atherosclerosis model by carotid artery ligation, in which we verified the role of Piezo1 in DF‐related atherosclerosis." (PMID 39450718, 2024). "We have also unraveled that Piezo1 is involved in macrophage-mediated inflammatory diseases, such as AD, pulmonary inflammation, atherosclerosis, and OA." (PMID 37334369, 2023). "This section focuses on the in-depth investigation of the role of Piezo1 in macrophage-mediated inflammatory diseases, such as Alzheimer’s disease (AD), pulmonary inflammation, atherosclerosis, and osteoarthritis (OA)." (PMID 37334369, 2023). "By inhibiting chemically and mechanically activated Piezo1 channels, salvianolic acid B ameliorates atherosclerosis." (PMID 38066464, 2023). "Piezo1 was proposed to participate in macrophage inflammatory activation, proliferation, and migration/infiltration to mediate the progression of atherosclerosis." (PMID 37588590, 2023). "The role of Piezo1 mechanotransduction in vascular, immune/inflammatory cells, indicates that Piezo1 is involved in atherosclerosis, therefore Piezo1 is a promising candidate for therapeutic innovation against atherosclerosis and other CVDs." (PMID 35173527, 2022). "This review discusses mechanistic insight about this matter and highlights the drugability and therapeutic potentials consistent with emerging functions Piezo1 in various mechanisms of atherosclerosis." (PMID 35173527, 2022). "Altogether, these data demonstrate and validate the drugability and therapeutic potential of Piezo1 in cardiovascular, particularly atherosclerosis." (PMID 35173527, 2022). "Piezo1 has been considered a therapeutic target for diverse disorders, including atherosclerosis and kidney fibrosis, and with this publication should now also be considered a viable target for disuse atrophy." (PMID 35575087, 2022). "Lastly, further elucidation of Piezo1 mechanisms regulating atherosclerosis should be the priority for future research as initial step for developing novel and effective therapeutic strategies for treating atherosclerosis." (PMID 35173527, 2022). "Altogether these functions demonstrate Piezo1 potentiality as promising target for novel therapeutic innovation against atherosclerosis and other CVDs." (PMID 35173527, 2022). "To bring the awareness of mechanosensitive Piezo1 role in atherosclerosis and its therapeutic potentials we review recent literature to highlight its involvement in various mechanisms of the disease." (PMID 35173527, 2022). "Although our findings provide insight into the relationship between Piezo1 activation and deleterious effects on endothelial cells, it is important to note that development of atherosclerosis is a chronic process and is best studied in animals." (PMID 33298523, 2021).
atherosclerosis (continued). "Our data also implicate that Piezo1 is a possible target of RRP in the treatment of atherosclerosis." (PMID 33568993, 2020). "Additionally, some natural products, such as quercetin, have been found to alleviate the progression of atherosclerosis by downregulating Piezo1-mediated Ca2+ signaling, showing promising potential for application (Wang YM." (PMID 41195420, 2025). "Under blood flow stimulation, the opening of the Piezo1 channel leads to an increase in intracellular Ca2+ concentration, which activates inflammatory responses and cell proliferation, accelerating the formation of atherosclerosis." (PMID 41195420, 2025). "Finally, we propose the Piezo1 channel as a potential therapeutic target in atherosclerosis to counteract the overstimulated lipid metabolism in VSMCs." (PMID 38145971, 2024). "We evaluated the long‐term effect of Piezo1 on atherosclerosis." (PMID 39450718, 2024). "Although the mechanism by which OSS mediates inflammation activation in ECs and atherosclerosis remains an unsolved mystery, recent studies suggest that Piezo1, a mechanically sensitive protein, could be a key breakthrough." (PMID 39450718, 2024). "However, little is known about Piezo1's biomechanical sensing role in the cardiovascular system, especially in atherosclerosis, which is closely related to shear stress of blood flow." (PMID 39450718, 2024). "The present study highlights PIEZO1 as a potential novel target for atherosclerosis intervention." (PMID 39107572, 2024). "Our findings propose PIEZO1 as a novel and potential therapeutic target in atherosclerosis." (PMID 39107572, 2024). "Our study suggests an important role for Piezo1 in oxLDL uptake and atherosclerosis." (PMID 39544498, 2024). "Thus, we used the pharmacological inhibitor GsMTx4 to explore the in vivo role of Piezo1 on atherosclerosis." (PMID 39450718, 2024). "Taken together, our research indicates that Piezo1 could be a potential therapeutic target for atherosclerosis." (PMID 39450718, 2024). "In this study we focused on the effect of pharmaceutical activation of PIEZO1 in macrophages in context of atherosclerosis, though our observation could reflect cumulative effects of systemic Yoda1 administration." (PMID 39107572, 2024). "In fact, as a mechanical ion channel protein, Piezo1 plays an important role in the response of endothelial cells to blood flow stress and shear stress, which is related to the occurrence and development of cardiovascular diseases such as atherosclerosis." (PMID 38690080, 2024). "A significant decrease in PIEZO1 levels in macrophages and foam cells may exacerbate atherosclerosis, prolonging foam cell presence within lesions and intensifying the inflammatory microenvironment." (PMID 39107572, 2024). "In this study, we evaluated the role of Piezo1 in atherosclerosis in vivo." (PMID 39450718, 2024). "Hence, we have explored the functional role of PIEZO1 in macrophages through in vitro and in vivo experiments to harness the therapeutic potential of PIEZO1 in the context of atherosclerosis." (PMID 39107572, 2024). "Studies revealed that Piezo1 promotes atherosclerosis formation by regulating the NF-κB pathway in vascular endothelial cells and can activate membrane-type matrix metalloproteinase(MMP)-1 and MMP-2 to promote angiogenesis, thereby promoting unstable plaque formation." (PMID 35751027, 2022). "As a mechanosensitive ion channel, Piezo1 senses the mechanical stimulation of blood vessels by local blood flow and converts them into chemical signals to regulate various biological processes such as inflammation and angiogenesis during atherosclerosis." (PMID 35751027, 2022). "As a critical mechanosensitive ion channel in endothelial cells, PIEZO1 plays diverse roles in endothelial shear stress sensing, nitric oxide (NO) generation, vascular tone, angiogenesis, atherosclerosis, vascular permeability and remodeling, blood pressure regulation, etc." (PMID 35883633, 2022).
atherosclerosis (continued). "Therefore, a deeper exploration of Piezo1 biology and translation towards the clinic will be a novel strategy for treating atherosclerosis and other CVDs." (PMID 35173527, 2022). "This stretch-induced plasticity of EC could augment atherosclerosis progression, and might be Piezo1-dependent." (PMID 35173527, 2022). "However, endothelial Piezo1 mediates pathological responses to pressue and is involved in atherosclerosis progression and inflammatory signaling." (PMID 33298523, 2021). "However, if the VECs are affected by eddy currents, activated Piezo1 will promote atherosclerosis development through the NF-κB pathway." (PMID 33568993, 2020). "Piezo1 is a possible target of RRP in the treatment of atherosclerosis." (PMID 33568993, 2020). "We show that Piezo1 plays a pivotal role in sensing stiff environments, modulating the expression of key uptake transporters, enhancing oxLDL accumulation, and leading to macrophage foam cell formation in vitro and the development and progression of atherosclerosis in vivo." (PMID 39544498, 2024). "However, the specific role of Piezo1 in atherosclerosis remains to be fully elucidated." (PMID 39450718, 2024). "Finally, we evaluated the role of Piezo1 in modulating atherosclerosis in vivo using a mouse model." (PMID 39544498, 2024). "Hence, through calcium, Piezo1 may contribute to atherosclerosis, though further study is required for this concept." (PMID 35173527, 2022). "Piezo1 discovery, emergence of its roles in various aspects of cardiovascular and rapid development of its research demonstrated a promising potential of the field towards novel therapeutic innovation for clinical application targeting atherosclerosis and other CVDs." (PMID 35173527, 2022). "Various mechanical cues sensed by Piezo1 affect multiple signaling pathways, which lead to alterations in functions, phenotype, gene expressions and cell behavior including proliferation, migration, apoptosis and remodeling, the crucial features of atherosclerosis." (PMID 35173527, 2022). "Having demonstrated that shear force activates Piezo1 which can disrupt AJs and form paracellular gaps in confluent monolayers, we next evaluated the effects of Piezo1 on endothelial cell activation and adhesion protein expression, which are two of the early processes in atherosclerosis." (PMID 33298523, 2021). "Finally, our study reveals Piezo1 as a possible target of RRP in the treatment of atherosclerosis." (PMID 33568993, 2020). "First, while we established the protective role of the Piezo1/BHLHE40/SLC7A11 axis in LPS-induced sepsis, its function in chronic vascular diseases such as atherosclerosis requires validation in respective animal models and clinical specimens." (PMID 41372156, 2025). "The mechanosensor Piezo1 and the downstream transcription factors c‐JUN and ETS1 regulate KDM5B expression, and KDM5B potentially contributed to atherosclerosis by regulating endothelial inflammation." (PMID 39643939, 2024). "Recent studies in the author's laboratory have found that silencing the expression of Piezo1 in human umbilical vein endothelial cells (HUVEC) and murine liver endothelial cells (MLEC) has a protective effect against atherosclerosis." (PMID 36247424, 2022). "We showed that endothelial KDM5B expression induced by d‐flow was regulated by Piezo1 and KDM5B may contributes to atherosclerosis potentially by regulating endothelial cell inflammation." (PMID 39643939, 2024). "Therefore, the relationship between Piezo1 and TRPV4 in the endothelium and initiation and perpetuation of atherosclerosis is more complicated than what can be studied in vitro." (PMID 33298523, 2021).
atherosclerosis (continued). "Although our study links mechanotransduction to vascular inflammation via the Piezo1/BHLHE40/SLC7A11 axis, validation in disease models such as atherosclerosis or other cardiovascular pathologies is lacking." (PMID 41372156, 2025).